FKBP5 (FKBP prolyl isomerase 5)
Diseases named in the same sentence as FKBP5 in open-access papers (continued):
Sharing a sentence is not in itself a finding about the gene and the disease.
tumor (continued). "Whilst the number of samples available between W1 and W3 was too small to detect any significant changes in individual gene expression, comparison of W2 and W3 showed that FKBP5 increased in 80% of the tumours in W3 and this was borderline significant." (PMID 31754627, 2019). "While tumor volume was the same between untreated shLuc control and shFKBP5 groups, it was significantly reduced in the FKBP5 silencing group following taxol treatment (P < 0.001)." (PMID 25460502, 2014). "Representative animals showed reduced tumor size following silencing of FKBP5 and treatment with taxol." (PMID 25460502, 2014). "FKBP5 has been shown to either promote or suppress tumor growth through its regulation of different signaling pathways in specific tissue environments." (PMID 25460502, 2014). "Genotype-phenotype association studies were performed using the SNPs identified during FKBP5 resequencing, and the phenotypes included overall survival and FKBP5 gene expression in tumor samples." (PMID 23936393, 2013). "Next, genotype-phenotype association studies were performed with overall survival as well as with FKBP5 gene expression in tumor using the same samples in which resequencing had been performed, followed by functional genomics studies." (PMID 23936393, 2013). "Collectively, this series of experiments suggests that FKBP5 functions as a tumor suppressor by negatively regulating the Akt pathway in vivo." (PMID 22590527, 2012). "There was a dramatic increase of tumor size in FKBP5 knockdown mice compared with control mice, indicating that FKBP5 is a potential tumor suppressor." (PMID 22590527, 2012). "Similar to its expression pattern, FKBP5 has been shown to either promote or suppress tumour growth through its regulation of different signalling pathways in a specific tissue environment." (PMID 21119664, 2011). "The dual role of FKBP5, whether functioning as an oncogene or a tumor suppressor, may be contingent on the tissue type and variations among the pathways expressed in those specific tumors." (PMID 38786025, 2024). "Correlative elaboration of key molecules including FCER1G, ZGMM, KIR2DL4, KIR3DH5, KLRC1, KLRB1, and FKBP5 among the 5 cell‐type clusters in evolutionary development trajectory of NKT for immune escalation against evasion of vital tumor cells and mutants was further illustrated by Violin plots." (PMID 37693048, 2023). "In our study, FKBP5 is highly expressed in a variety of tumor tissues." (PMID 35865544, 2022). "FKBP5 is suggested to be a tumor suppressor in the AKT signaling pathway." (PMID 34895219, 2021). "To assess whether the modulation effects of FKBP5 on txr exists in vivo, we used a mouse tumor xenograft model." (PMID 25460502, 2014). "Ectopic expression of FKBP5 (flag-FKBP5) induced AR expression in non-tumor HEK293T cells." (PMID 25460502, 2014). "Therefore, low FKBP5 expression renders tumor cells resistant to many chemotherapeutic agents, including gemcitabine." (PMID 22590527, 2012). "Down regulation of FKBP5 results in decreased PHLPP-Akt interaction and increased Akt phosphorylation at the Ser473 site, suggesting that FKBP5 may function as a tumor suppressor, an important fact contributing to chemoresistance." (PMID 22590527, 2012). "Whether FKBP5 functions as an oncogene or a tumour suppressor might depend on the tissue type and differences among pathways expressed in those tumours." (PMID 21119664, 2011). "In summary, FKBP5 has altered expression levels in many different tumours." (PMID 21119664, 2011). "Given the similarities between the immune microenvironment at the maternal–fetal interface and the tumor microenvironment in terms of immune metabolic reprogramming, hypoxic oxidative stress, etc., we hypothesized that FKBP5 may act as a “molecular switch” for immune homeostasis." (PMID 41271936, 2025). "Therefore, FKBP5 might function as a tumor suppressor, and levels of FKBP5 would affect cell response to chemotherapy." (PMID 22590527, 2012).
tumor (continued). "In addition to the role of FKBP5 in chemoresistance, based on our xenograft models it could also function as a tumor suppressor through negative regulation of the Akt pathway." (PMID 22590527, 2012). "Therefore, FKBP5 might also function as a tumour suppressor in the AKT signalling pathway, similar to phosphatase and tensin homologue (PTEN)." (PMID 21119664, 2011). "We prioritized FKBP5 (HP pharmacodynamics) and CLDN4 (tumor baseline) as the main candidates; TSPO and SGK1 are reported as exploratory." (PMID 41614938, 2026). "Genes with reported anti-tumor functions, including SCGB1D2 (Secretoglobin Family 1D Member 2, lipophilin B), FKBP5, CD52, DLK1, GALNT9, GNG2, GDNF, and TMEM35A, were significantly upregulated after CUDC-907 + MPA treatment and validated by RT-PCR." (PMID 41262902, 2025). "FKBP5 downregulation reduced tumor aggressiveness in KYSE70 cells, and clinical samples showed significantly worse survival rates in patients with high FKBP5 expression (OS: P=0.02; RFS: P=0.04)." (PMID 41041863, 2025). "FaDu–mock, FaDu-ALOX12, FaDu-FKBP5, MCF-7–mock, MCF-7-ALOX12, and MCF-7-FKBP5 mice were sacrificed, and the tumor weights were measured on the 48th day." (PMID 39766798, 2024). "Across tumor types, HSD11B1 expression correlated positively with expression of the glucocorticoid-responsive genes TSD22D3 (GILZ), DUSP1, and FKBP5." (PMID 37471141, 2023). "Of note FKBP5, a putative PRG, increased in 16 of the 20 tumours and this neared statistical significance (FC 1.6, BH = 0.051)." (PMID 31754627, 2019). "For this comparison, FKBP5, a putative PRG, was the most significant gene and showed the greatest fold-change (FC 1.5, p = 0.0057, BH = 0.23), increasing in 24 of 32 tumours in W3." (PMID 31754627, 2019). "Activity of the Akt pathway is significantly higher in FKBP5 knockdown SU86 xenografts than that in wild type SU86 xenografts and these observations correlated with higher tumor growth rates in shFKBP5 mice." (PMID 22590527, 2012). "Starting on the third day after injection, the tumor volume formed at the injection site was measured at intervals of 3 days, and the data were recorded for mice injected with FaDu–mock, FaDu-ALOX12, FaDu-FKBP5, MCF-7–mock, MCF-7-ALOX12, and MCF-7-FKBP5 cells." (PMID 39766798, 2024). "Furthermore, the pivotal nodes of the lncRNA–mRNA interaction network, including NEAT1, PGAP1, FKBP5 and CDON, were also validated by qRT–PCR and found to be downregulated in the EMPD tumor group." (PMID 34895219, 2021). "In the ex vivo analysis of the VCaP tumor samples for effects on the AR signaling pathway, we found a significant reduction of FKBP5 and TMPRSS2 expression after enzalutamide treatment, but no significant changes were seen in the BAY-155 treated study arm." (PMID 31947537, 2020). "Furthermore, growing pieces of evidence have demonstrated that FKBP5 down‐regulates p‐AKT and acts as a tumour suppressor." (PMID 33135363, 2020). "Additionally, while lower in global rankings, several genes including COL6A3 (extracellular matrix remodeling), FKBP5 (glucocorticoid signaling), IGFBP2 (tumor invasion and angiogenesis), and TPM2 (cytoskeletal stability) appeared prominently in local SHAP plots for specific cancer samples." (PMID 40941703, 2025). "The three mRNAs, PGAP1, FKBP5 and CDON, may act as tumor suppressors in EMPD." (PMID 34895219, 2021). "Besides, FKBP5 could promote the interaction between AKT and PHLPP as a scaffolding protein and influence the phosphorylation of downstream FOXO3 as a tumor suppressor." (PMID 32760250, 2020). "WGCNA highlighted module-level structure rather than generic hubs, a tumor-enriched tight-junction/ECM module containing CLDN4, and an HP-enriched steroid/PPAR–lipid module containing FKBP5." (PMID 41614938, 2026). "Accordingly, while FKBP5 serves as a measure of HP exposure in pre-tumoral tissue, CLDN4 represents the baseline for tumor structure that HP is not expected to alter on its own." (PMID 41614938, 2026).
cancer (33 papers, 2011 to 2026). A tumor composed of atypical neoplastic, often pleomorphic cells that invade other tissues. "Our findings highlight several known joint susceptibility loci for CAD and cancer, including FKBP5, CUX2, and LMOD1, validating the pleiotropy analysis approach employed by PLACO." (PMID 40874306, 2025). "Our results are in alignment with this report because we found ALOX12 and FKBP5 somatic mutations in cancer patients who had experienced traumatic life events." (PMID 39766798, 2024). "Protein, encoded by the FKBP5 gene, is responsible for stress and metabolic-related disorders, including cancer." (PMID 36531220, 2022). "FKBP5 is implicated in regulating cancer-related signaling pathways that can lead to chemoresistance in cancer patients." (PMID 36430579, 2022). "Tumorigenesis risk is associated with upregulated periodic cancer cell cycle genes (Fkbp5, Acsl3) and enzymatic mutagenesis genes (Cy3a44)." (PMID 34202278, 2021). "Previous studies conducted on various cancer types, showed that upregulation of FKBP5 gene expression is associated with drug resistance." (PMID 33233407, 2020). "These ALOX12 and FKBP5 somatic missense mutations may be induced via the psychological stress experienced by these patients, which may also contribute to cancer initiation and progression." (PMID 39766798, 2024). "Previous studies showed that upregulation of FKBP5 is associated with drug resistance in various cancers (including breast, prostate, myeloma, acute lymphoblastic leukemia, melanoma) following treatment with antineoplastic agents (FK506, rapamycin, dexamethasone, irradiation)." (PMID 25460502, 2014). "A deeper examination of the feature importance of the cancer detection model has revealed the top five transcripts at play: FKBP5, TMSB4XP8, MTRNR2L12, HBB, and SPDYC." (PMID 38887841, 2024). "The relationship between cancer and FKBP5 and ALOX12 gene expression has been evaluated in several studies, and the results support our findings." (PMID 39766798, 2024). "The exploration of the feature importance of the cancer detection model has pinpointed the top five transcripts characterized by their largest weight on prediction outcomes: FKBP5, TMSB4XP8, MTRNR2L12, HBB, and SPDYC." (PMID 38887841, 2024). "FKBP5 plays an important role in immune regulation, the occurrence and treatment of cancer, and the regulation of steroid hormones." (PMID 38665092, 2024). "It was observed that the expression of FKBP5 is both upregulated and downregulated in human cancers." (PMID 39766798, 2024). "The Protein Atlas also shows that ALOX12 and FKBP5 have low expression both in cancer tissue and cancer cell lines." (PMID 39766798, 2024). "We first searched the Protein Atlas to understand ALOX12 and FKBP5 expression status in cancer cell lines and cancer tissues." (PMID 39766798, 2024). "For example, non-coding RNA molecules such as circular RNAs (circRNAs) and long non-coding RNAs (lncRNAs) can contribute to the progression of autoimmune diseases and cancer through miRNA/FKBP5 axis regulation." (PMID 37398599, 2023). "FK506‐binding protein 5 (FKBP5) was reported to participate in the regulation of steroid hormone receptor, stress‐related mental disease, cancer and other physiological or pathological processes." (PMID 34028189, 2021). "The suggestion of a possible role of FKBP5 in the development and progression of different types of cancer has stemmed from several studies." (PMID 34071989, 2021). "In cancer etiology and chemoresistance, FKBP5 plays a role in cell apoptosis or death via the glucocorticoid receptor (GR) signaling pathway, NF-kB pathway and AKT–PHLPP pathways." (PMID 34895219, 2021). "In several human cancer tissues, a relevant role for FKBP5 in sustaining cancer cell growth and aggressiveness has been documented." (PMID 33233407, 2020). "In this review, we will focus on the recently discovered role of FKBP5 in cancer aetiology and response to antineoplastic therapy." (PMID 21119664, 2011).
cancer (continued). "Subsequent paragraphs will focus on the discovery of the role of FKBP5 in cancer aetiology and chemoresistance." (PMID 21119664, 2011). "Recent evidence also indicates that FKBP5 methylation significantly influences malignant tumors." (PMID 41664704, 2026). "Our results clearly indicate that psychological stress may induce cancer development via increased somatic missense mutations in ALOX12 and FKBP5 genes." (PMID 39766798, 2024). "For example, FKBP5 is a target for anti-depressants and anti-cancer drugs." (PMID 37398599, 2023). "Many studies have indicated a significant negative association between FKBP5 and the severity of different types of cancer." (PMID 37398599, 2023). "The Akt kinase pathway is regulated by FKBP5, and the FKBP5/AR complex may affect the sensitivity of cancer cells to paclitaxel by regulating the expression of the txr gene." (PMID 35886904, 2022). "Since FKBP5 represents a scaffold protein and the AR is upregulated in tumors and chemoresistant cancer cells, we examined the possibility that these proteins may interact." (PMID 25460502, 2014). "Both overexpression and downregulation of FKBP5 have been observed in human cancers." (PMID 21119664, 2011). "This is because, in cancer patients, the A549, MCF-7, and FaDu cell lines express lower levels of ALOX12 and FKBP5 mRNAs when compared to the cancer-free patient group, as indicated in our qRT-PCR results." (PMID 39766798, 2024). "The expression status of ALOX12 and FKBP5 genes in patients with or without cancer and several cancer cell lines was also examined using the qRT-PCR method." (PMID 39766798, 2024). "Accordantly, FKBP5 that acts antagonistically to the function of FKBP4 was found to confer chemosensitization via negatively regulating AKT in several types of cancer cells." (PMID 35981890, 2022). "The cancer related category apoptosis was over-represented with both up- and down-regulated genes, represented by two up-regulated genes (TNS3, EMP1) and five genes down-regulated (DNASE1L2, CXCR4, Gal-7, FKBP5, SGK1)." (PMID 25867603, 2015). "FKBP5 is involved in several signaling pathways, including hormone signaling, irradiation-induced NF-κB activation, and chemotherapy-induced Akt-PHLPP pathways, exerting important roles in cancer development and chemoresistance." (PMID 25460502, 2014). "The expression status of ALOX12 and FKBP5 genes on patients with or without cancer and several cancer cell lines demonstrated that both ALOX12 and FKBP5 mRNA levels were downregulated only in cancer patients and cancer cell lines but not in cancer free control groups." (PMID 39766798, 2024). "We noted that ectopic expression of FKBP5 resulted in moderate increase of AR in SKOV3 cells, whereas no significant increase of AR was detected in HEK293T cells, suggesting the possibility that higher survival signals may be present in cancer cells." (PMID 25460502, 2014). "The expression status of ALOX12 and FKBP5 genes in patients with or without cancer and several cancer cell lines demonstrated that both ALOX12 and FKBP5 mRNA levels were downregulated in cancer patients and cancer cell lines (A549, MCF-7, and FaDu)." (PMID 39766798, 2024).
infection (9 papers, 2012 to 2023). The state of being infected such as from the introduction of a foreign agent such as serum, vaccine, antigenic substance or organism. "After ad-mRFP-GFP-LC3B infection, autophagic flux increased with high FKBP5 expression, while it decreased in response to FKBP5 knockdown." (PMID 32760250, 2020). "During primary infection, hub protein such as Elavl1, Btg2, Fkbp5, Hug, Hsp90a.1 are also top in the betweenness ranking." (PMID 25341656, 2014). "In a ferret AIV infection model, it is suggested that the up-regulation of FKBP5 is a physiological response of lung cells to the increase of glucocorticoid, which facilitates the suppressive effect of glucocorticoid on pro-inflammatory cytokine production." (PMID 22390870, 2012). "The female mice exhibited higher expression levels of AKT1, BTK, CCL9, and LSP1 (KO, 1A0), PPARG (KO, 1A0, and 6A2), CFLAR, and ERP44 (1A0, 6A4), CCL9 (KO, 1A0, and 6A4), RCC2, and RELA (KO), KAT2B (6A2) and FKBP5 (1A0, 6A2, and 6A4) compared to males in response to infection." (PMID 32670284, 2020). "Six of these genes were predicted to be involved in host immune response to infection: PTN on BTA4, AP3B1 on BTA10, HSF1on BTA14, SHARPIN on BTA14, TRAF4 on BTA20 and FKBP5 on BTA23." (PMID 26960806, 2016). "Both ABCG2 and FKBP5 were also identified as DEG in the recent transcriptional comparison of uninfected quarters from healthy and mastitic animals, suggesting that their differential expression was due to the infection of neighbouring quarters with E. coli." (PMID 23324411, 2013). "However, in response to infection, male mice exhibited higher expression levels of CFLAR, and FKBP5 (KO, 1A3), AKT1, and CCL9 (1A3, 6A2), C1QC (6A2), LSP1 (1A3, 6A2, and 6A4), CKAP2, and KAT2B (KO), TACC2 (1A0), RCC2 (1A3, 6A2), PPARG (1A3, 6A4), and ERP44 (6A2) compared to females." (PMID 32670284, 2020).
metabolic disorders (9 papers, 2018 to 2026). "This gene regulates the glucocorticoid receptor (GR), and aberrant FKBP5 methylation is associated with psychiatric and metabolic disorders." (PMID 41664704, 2026). "The gene encoding the immunophilin FK506 binding protein 5 (FKBP5) has been implicated in psychiatric, neuroendocrine, and metabolic disorders." (PMID 30619472, 2018). "We analyzed by pyrosequencing nine CpG-dinucleotides in intron 2 of FKBP5 that were implicated in metabolic disorders in previous studies and flanked an experimentally validated GRE." (PMID 29951131, 2018). "Moreover, it remains to be determined whether altered FKBP5 methylation patterns in SAT are reflected in blood, which could be used to assess potential risk of developing metabolic disease." (PMID 32958048, 2020). "FKBP5 modulates GR sensitivity, linking it to stress-related disorders, including PTSD and metabolic diseases." (PMID 40017583, 2025).
cardiovascular disease (8 papers, 2014 to 2022). "FKBP5 expression is associated with insulin resistance, type 2 diabetes, and obesity, which are closely related to cardiovascular disease." (PMID 32547886, 2020). "More recently, hypermethylation of two CpG sites in FKBP5 intron 2 in peripheral blood were associated with metabolic risk and cardiovascular disease traits, including BMI and WC, in individuals with T2D." (PMID 32958048, 2020). "Further work should aim to assess the longitudinal association of FKBP5 with cardiovascular disease and glycemic outcomes in T2DM as a first step in understanding potential preventive and treatment-related interventions targeting the HPA axis." (PMID 29951131, 2018). "Also, a study by Ortiz and colleagues reported an association between FKBP5 intronic methylation and the risk of cardiovascular disease in T2D patients." (PMID 35787810, 2022). "Additionally, there is evidence that FKBP5 may interact with inflammatory factors in cardiovascular diseases." (PMID 32760250, 2020). "Given its importance in the function of the HPA axis via regulation of the glucocorticoid receptor, if FKBP5 is shown to be associated with metabolic syndrome, T2DM, and cardiovascular disease, it may serve as a promising target for interventions aimed at restoring HPA axis function." (PMID 29951131, 2018). "However, FKBP5 methylation has not been studied in individuals with T2DM, or in the context of specific measures of metabolic and cardiovascular disease." (PMID 29951131, 2018).